ALB (albumin)
Diseases named in the same sentence as ALB in open-access papers (continued):
Sharing a sentence is not in itself a finding about the gene and the disease.
protein deficiency (17 papers, 2009 to 2025). "Protein deficiency is frequently monitored in clinical practice by serum protein levels such as albumin and prealbumin." (PMID 40944141, 2025). "At baseline serum albumin levels of both the study groups were below the normal range (3.5–5.0 g/dL) which indicated protein deficiency, secondary to poor dietary intakes or presence of infections." (PMID 36962678, 2022). "Protein deficiency (serum albumin levels below 3 g/dl) associated with bariatric surgery is an unusual and ominous event." (PMID 35800664, 2022). "Protein deficiency can be evaluated by both albumin or pre-albumin serum levels, with the latter representing a more reliable marker of acute malnutrition thanks to its shorter half-life of 24–48 h." (PMID 34066564, 2021). "Total protein, albumin, pre-albumin, transferrin, and lymphocyte count should be used to identify patients with protein deficiency." (PMID 34066564, 2021). "Plasma albumin levels indicated a protein deficiency, with an average value of 29.4 ±5.6 g/L." (PMID 38140320, 2023). "Serum albumin is possibly a more sensitive marker of protein deficiency than red blood cell counts." (PMID 27532039, 2016). "As a result, regular measurement of albumin in the early postoperative period is of no use in diagnosing protein deficiency and postoperative malnutrition, which are visceral proteins." (PMID 35800664, 2022). "Considering the changes in dietary intake and body weight, this suggests that the decrease in albumin is due more to the effects of inflammation, rather than due to energy or protein deficiency." (PMID 35949598, 2022). "On the other hand, although hepatic albumin gene expression is suppressed by protein deficiency, the gene expression levels were not significantly different between groups in our study." (PMID 30090810, 2018).
renal carcinoma (17 papers, 2010 to 2025). A carcinoma arising from the epithelium of the renal parenchyma or the renal pelvis. "Lower levels of albumin were generally associated with increased odds ratios for most cancers (except for prostate and renal cancer in men, where there was an inverse association)." (PMID 40335498, 2025). "Albumin levels can be indicative of renal cancer prognosis, and patients of metastatic renal cell carcinoma with low serum albumin have a shorter progression-free survival." (PMID 35655917, 2022). "The level of ALB correlates with the severity of renal cancer." (PMID 41439108, 2025). "Furthermore, early postoperative serum albumin level has been shown to predict survival following nephrectomy for curative renal cancer." (PMID 38500655, 2024). "A selective combination of C-reactive protein and albumin (termed the modified Glasgow Prognostic Score, mGPS) has been shown to have prognostic value, independent of tumour stage, in lung, gastrointestinal and renal cancers." (PMID 21266974, 2011).
sarcoma (17 papers, 1984 to 2025). A usually aggressive malignant neoplasm of the soft tissue or bone. "Examples include effective docetaxel-loaded mPEG-PLA nanoparticles in sarcoma-bearing mice and albumin-paclitaxel (nab-paclitaxel/AbraxaneTM) in osteosarcoma mice." (PMID 37007160, 2023). "Because secreted protein acidic and rich in cysteine (SPARC) shows high binding affinity to albumin, a study has proved that pediatric sarcoma xenografts expressing SPARC would show enhanced uptake and accumulation of nab- paclitaxel." (PMID 35223497, 2022). "Both pretreatment serum CRP (C-reactive protein) level and ALB (albumin) level have been found to be predictive of survival for multiple malignancies including sarcoma." (PMID 31998420, 2020). "For instance, in a mouse sarcoma model (C57/RL6J) injected with 3H-raffinose-labeled albumin, at least 2–3-fold greater levels of 3H were observed in the lysosomes of tumors when compared with lysosomes of normal tissue." (PMID 25161624, 2014). "Such an asymmetric distribution was also reported by Boucher and his colleagues in their study with mice involving intratumoral infusion of Evans blue-albumin into sarcoma HSTS 26T." (PMID 24619021, 2014). "Increases in TP, A/G, albumin were observed in mice implanted with S180 sarcoma (group III), and the degrees of change were big, and related toxicological changes were evident." (PMID 22754316, 2012). "Studies on the treatment of sarcomas with nanoparticle albumin-bound paclitaxel (nab-paclitaxel)." (PMID 35223497, 2022). "As nab-paclitaxel or other chemotherapy agents that bind to albumin such as aldoxorubicin are evaluated in sarcoma, the use of SPARC as a predictive biomarker might be considered." (PMID 27544129, 2016). "Future studies might focus on prospective evaluation of SPARC expression in sarcoma, especially in a cohort of patients treated with albumin-bound agents." (PMID 27544129, 2016). "The positivity of SPARC indicates that there may be greater delivery of albumin-bound paclitaxel to the malignant sarcoma, since SPARC is a facilitator that allows more chemotherapeutic agents to concentrate in the surrounding tumoral microenvironment." (PMID 23895135, 2013). "In this study we compared the efficiency, cytotoxicity and protein targeting of different commercially available transduction reagents by transducing a well-studied fluorescently labelled protein (Atto488-bovine serum albumin) into cultured human sarcoma cells." (PMID 23285056, 2012). "Cells of osteogenic sarcoma line 791T were treated in vitro with a selectively cytotoxic methotrexate-human serum albumin-monoclonal antibody conjugate at concentrations which were toxic but allowed the "escape" of a small number of tumour cell colonies (less than 0.3% compared with controls)." (PMID 6586198, 1984). "In this study, non-aggregated colloidally stable CeO2NPs conjugated with murine serum albumin (MSA) were synthesised and administered intravenously to mice with xenografted subcutaneous sarcoma tumours." (PMID 37570527, 2023). "Since both of the GPS (Glasgow prognostic score) and CAR (C-reactive protein to albumin ratio) are based on the combination of CRP and ALB, we conducted a meta-analysis to evaluate the prognostic role of these two parameters for sarcoma patients." (PMID 31998420, 2020). "Mice implanted with S180 sarcoma showed a significant increase in serum AST, ALT and ALP activities, liver MDA level, decrease in serum WBC, TP, ALB, A/G, TNF-α and IFN-γ, and liver GSH, SOD, CAT, GSH-Px and GR activities." (PMID 22754316, 2012). "In this study, a DCE-MRI-based computational model was developed for predicting albumin tracer distribution following CED in the lower limb of a mouse (C3H) inoculated with murine sarcoma cells (KHT), as opposed to systemic delivery which was modeled in our previous studies." (PMID 24619021, 2014).
acute myeloid leukemia (16 papers, 2019 to 2026). Acute myeloid leukemia (AML) is a group of neoplasms arising from precursor cells committed to the myeloid cell-line differentiation. "A retrospective study also indicated that lower serum albumin levels predicted a higher 60-day mortality rate from acute myeloid leukemia." (PMID 38500655, 2024). "The close monitoring of acute myeloid leukaemia (AML) patients in routine care includes an array of biochemical specimens, amongst these C-reactive protein (CRP) and plasma albumin (PA) that are performed repeatedly during the course of AML." (PMID 32209087, 2020). "The selenocyanate compound p-XSC (p-xyleneselenocyanate) was shown to be highly toxic to the murine acute myeloid leukemia cell line C1498 in a concentration-dependent manner, while its cytotoxicity was completely abrogated after addition of 1% BSA (bovine serum albumin) in the complete medium." (PMID 31554226, 2019). "A recent report on acute myeloid leukemia patients not eligible for stem-cell transplantation illustrates that a combined assessment of CRP and albumin is of interest in myeloid malignancies in general." (PMID 36900271, 2023).
Autoimmunity (16 papers, 2014 to 2025). The occurrence of an immune reaction against the organism's own cells or tissues. "Therapies with mRNA coding for IL-2 (eventually mutated or fused to albumin) are promising in the context of cancer and autoimmunity." (PMID 39120273, 2024). "The identification of ALB as a central hub protein emphasizes its potential as a biomarker and therapeutic target for enhancing resistance to autoimmunity in aging populations." (PMID 40546301, 2025). "Serum albumin is a valuable biomarker for a variety of pathological conditions, including inflammation, ischemia, autoimmunity, and metabolic disorders." (PMID 38500655, 2024). "Animal studies showed that mice immunized with CEP-modified mouse serum albumin generated anti-CEP antibodies that consequently induced AMD-like lesions in the outer retina, suggesting that autoimmunity was associated with the initiation or progression of AMD." (PMID 25488058, 2014). "Our data showed that MRL/lpr mice displayed significantly lower spleen and kidney weight indices and higher levels of serum dsDNA antibodies, nRNP/Sm antibodies, urine albumin/creatinine ratio, and serum cystatin C, suggesting a damaged kidney function and high level of autoimmunity." (PMID 40761479, 2025). "By acting as a hapten, mercury can bind to a high-molecular-weight carrier protein, such as human serum albumin (HSA), causing the immune system to mistakenly “recognize” self-tissue as an invader and launch an immune response against it, leading to autoimmunity." (PMID 35366249, 2021). "We assessed lung perfusion using Technetium-99m macroaggregated albumin (MAA) SPECT-CT scans, clotting using coagulation and thromboelastrogram (TEG) tests, and autoimmunity to vascular and lung antigens using ELISA assays." (PMID 40519899, 2025). "A possible hypothesis for MOG and AQP4 antibody-associated autoimmunity triggered by a VZV infection is that the VZV infection causes a breakdown of the blood-brain barrier, as indicated by the common finding of an elevated CSF/serum albumin ratio in herpes zoster." (PMID 34737756, 2021). "IgA-BSA did not cross-react with milk proteins like casein, β-lactoglobulin, and γ-globulin, nor with autoantigens and human albumin, ruling out autoimmunity against self-proteins." (PMID 40507813, 2025). "TSH and albumin test results were normal and autoimmunity was negative." (PMID 34918683, 2021).
endometriosis (16 papers, 2013 to 2026). The growth of functional endometrial tissue in anatomic sites outside the uterine body. "Systemically, endometriosis has been associated with altered levels of acute-phase proteins such as fibrinogen and albumin, indicative of broader inflammatory and coagulation-related changes." (PMID 41590512, 2026). "We also compared the levels of total proteins and human serum albumin concentrations between blood plasma and peritoneal fluid to determine possible changes in peritoneum permeability associated to endometriosis." (PMID 31221043, 2019). "In this article we describe the potential value as diagnostic markers for endometriosis of two proteins (serum albumin and complement C3 precursor), previously identified as differentially expressed in women with endometriosis respect to healthy control by 2D gel analysis." (PMID 26759817, 2015). "Endometriosis has also been associated with significantly higher levels of lipid peroxide-modified rabbit serum albumin, malondialdehyde-modified low-density lipoprotein, and oxidized low-density lipoprotein as measured in serum and compared to tubal ligation cases." (PMID 23984345, 2013). "In this retrospective analysis, the fibrinogen-to-albumin ratio was significantly elevated in women with endometriosis compared to controls, consistent with the inflammatory nature of the disease." (PMID 41590512, 2026). "Albumin levels were slightly lower in the endometriosis group (median 44.85 g/L, IQR 42.70–46.73) than in controls (45.20 g/L, IQR 43.30–47.40; p = 0.08)." (PMID 41590512, 2026). "The calculated fibrinogen-to-albumin ratio (FAR) was significantly higher in the endometriosis group (median 0.0679, IQR 0.0588–0.0778) than in controls (0.0641, IQR 0.0559–0.0716; p < 0.01, Mann–Whitney U test)." (PMID 41590512, 2026). "This study explored the fibrinogen-to-albumin ratio (FAR) as a potential inflammatory biomarker in endometriosis by analyzing routinely collected preoperative laboratory data from a well-characterized surgical cohort." (PMID 41590512, 2026). "The titer for LPO-modified rabbit serum albumin was 0.49 ± 0.12 units in the endometriosis group and 0.2 ± 0.02 units in the healthy control group." (PMID 40722981, 2025). "Based on serum proteomic differential expression, a possible biomarker panel comprising zinc-alpha-2-glycoprotein, albumin, and complement C3 has been proposed for effective and non-invasive diagnosis of endometriosis." (PMID 32575462, 2020). "ELISA tests were performed on a cohort of endometriosis (n=100) and healthy patients (n=10) in order to confirm the differential expression of two proteins, complement C3 and human albumin identified through the proteomic approach described in Signorile and Baldi." (PMID 26759817, 2015). "Additionally, decreased serum albumin was associated with absent of endometriosis (P = 0.015), and elevated NLR was associated with more residual tumor (P = 0.047)." (PMID 28498842, 2017). "Based on multivariate analysis, the serum albumin (HR, 0.49; 95% CI, 0.27–0.91; P = 0.024), together with FIGO stage, residual tumor, preoperative ascites, and endometriosis were independent predictors for PFS." (PMID 28498842, 2017). "Interestingly, FF albumin and hemopexin, both implicated in oxidative burden mitigation, were identified as distinct proteins in women with endometriosis who conceived, compared to women with endometriosis who did not conceive." (PMID 28701210, 2017). "Adipose tissue can sequester BVD, but chronic inflammation (more common in higher BMI and endometriosis) may alter DBP and albumin levels, affecting BVD calculation." (PMID 40687539, 2025). "In the present study, the albumin concentrations were slightly higher, but insignificant, in endometriosis, when compared with the non-endometriosis and control groups (mean values: 4.45 g/dL, 4.29 g/dL and 4.26 g/dL, respectively)." (PMID 34356330, 2021).
endometriosis (continued). "Moreover, cyto-hub gene analysis revealed that CSNK2A1, CSNK2A2, TOP1, PRKACA, RBM39 (plasma), ALB, ACTB, GAPDH, FN1, APOA1 (serum), S100-A9, CXCL1, IL1RN, CSTA, S100-A8 (menstrual blood) and THBS1, ALB, CD44, ANXA2, and LUM (urine) were the top 5 proteins expressed in women with endometriosis." (PMID 39061077, 2024). "The fibrinogen-to-albumin ratio (FAR), a composite marker of systemic inflammation, has been proposed in both oncological and cardiovascular disease but has not yet been evaluated in endometriosis." (PMID 41590512, 2026). "Inflammation may drive adhesion formation, and the predictive value of the neutrophil percentage-to-albumin ratio (NPAR, the ratio multiplied by 10 for analysis), an emerging biomarker of systemic inflammation, in endometriosis pelvic adhesions has not been evaluated." (PMID 41329674, 2025).
fracture (16 papers, 2017 to 2025). "Previous studies indicated that the risk factors for dysphagia in older patients with hip fracture were low serum albumin level, female gender, mental disorientation following surgery, and reduced physical status (ASA III and IV)." (PMID 32397658, 2020). "The findings of this study indicated that serum albumin levels of ≥35 g·L−1 functioned as an independent protective factor for recurrent hip fractures following primary osteoporotic hip fracture surgery." (PMID 41294891, 2025). "Similarly, decreased albumin levels are a strong independent predictor of mortality after a hip fracture, and prealbumin also appears to be an important marker due to its better sensitivity to changes." (PMID 37238934, 2023). "We also found a close relationship between albumin and mortality following hip fracture." (PMID 28426743, 2017). "Our study differentiates itself by focusing on the combination of RDW, albumin parameters, and the RDW/albumin ratio as potential prognostic indicators of mortality in elderly hip fractures." (PMID 37701840, 2023). "In the intertrochanteric fracture group, hemoglobin levels were positively correlated with greater trochanter, intertrochanteric region, and whole hip region BMD (P < .05), while albumin levels were positively correlated with greater trochanter BMD (R = 0.191, P = .028)." (PMID 40550046, 2025). "Age, male, female, BUN, baseline glomerular filtration rate, preoperative albumin, preoperative creatinine, postoperative serum albumin, CCI index, and length of stay were not influencing factors for postoperative AKI in elderly patients with hip fracture (P < 0.05)." (PMID 40540489, 2025).
hematoma (16 papers, 2020 to 2025). A hematoma is a collection of blood from a vascular structure into an extravascular space. "Lower levels of serum albumin have been linked to larger hematoma volumes, heightened complication risks, and increased mortality rates in individuals diagnosed with ICH." (PMID 39099785, 2024). "Patients with low postoperative ALB levels are at higher risk of wound exudation, hematoma, and poor wound healing, resulting in late bedtime activity and poor exercise outcomes." (PMID 34906186, 2021). "Mice were subsequently sacrificed and their brains collected for measurement of vascular leakage via albumin radiotracing as well as blinded analysis of hematoma size." (PMID 40297702, 2025). "SHAP analysis identified hematoma volume as the most critical predictor, with secondary contributions from Glasgow coma score, white blood cell count, age, serum albumin, and systolic blood pressure, among others." (PMID 40534743, 2025). "Third, Nrf2 helps upregulate CD163 and CD36 expression in microglia; thus, we cannot exclude the possibility that the protective effect of albumin in promoting hematoma clearance is due to the contributions of other Nrf2 signaling pathways." (PMID 33708336, 2021). "Incorporating these risk factors into a logistic regression model for safety outcomes showed that six variables remained correlated with adverse events: admission mRS score, GCS score, and ADL score; hematoma volume at admission and discharge; and serum albumin level at admission." (PMID 41561342, 2025). "Additionally, systolic blood pressure on admission, baseline hematoma volume, and albumin on admission remained significant in the multivariate analysis (p = 0.009, p = 0.001, and p = 0.020, respectively)." (PMID 39344372, 2024). "Univariate analysis revealed that systolic pressure (P = 0.043), GCS (P < 0.001), hematoma volume (P < 0.001), serum Potassium (P < 0.001), blood glucose (P < 0.001), serum albumin (P = 0.016), and lactic acid (P < 0.001) on admission were significantly correlated with PMV." (PMID 37396763, 2023). "Hematoma Volume emerged as the most influential predictor of prognosis, followed by GCS, WBC, Age, Albumin, and SBP." (PMID 40534743, 2025). "Beyond traditional indicators like hematoma volume and GCS score, the study confirmed the independent predictive value of serum albumin, white blood cell count, and systolic blood pressure fluctuations for HICH's long-term prognosis." (PMID 40534743, 2025). "Furthermore, these patients tended to present with larger hematoma volumes, lower GCS scores, increased platelet counts, elevated admission blood glucose levels, increased fibrinogen levels, and decreased albumin levels." (PMID 39099785, 2024). "Our study aimed to investigate whether monocyte‐to‐albumin ratio (MAR), a novel marker of systemic inflammation, could predict hematoma expansion (HE) in patients with spontaneous intracerebral hemorrhage (ICH)." (PMID 39344372, 2024).